BRCA1 (BRCA1 DNA repair associated)
Diseases named in the same sentence as BRCA1 in open-access papers (continued):
Sharing a sentence is not in itself a finding about the gene and the disease.
cancer (continued). "WB results showed that the levels of METTL1 (p < 0.0001), BRCA1 (p < 0.0001) and m7G (p < 0.0001) in cancer tissues were significantly higher than those in adjacent tissues (all p < 0.0001)." (PMID 41430564, 2025). "Poly (ADP-ribose) polymerase inhibitors (PARPi) exploit DNA repair deficiency in germline BRCA1 and BRCA2 pathogenic variant (gBRCAm) cancers." (PMID 40360463, 2025). "Timely identification and management of elevated cancer worry are therefore critical components of comprehensive care for BRCA1/2 carriers." (PMID 40390061, 2025). "As there were differences in the number of variants in BRCA1 and BRCA2, gender ratios, and cancer types, we compared these outcomes separately." (PMID 40249378, 2025). "Breast cancer type 1 susceptibility protein (BRCA1) gene produces a breast and ovarian‐cancer‐specific tumour suppressor that plays roles in the control of the cell cycle checkpoint and maintenance of chromosomal stability." (PMID 40008534, 2025). "Pt#3 was found to be a carrier of BRCA1; indeed, a high incidence of early and severe cancer in this patient’s family has been documented." (PMID 40725177, 2025). "Clinically pathogenic variants, particularly those in high-penetrance genes such as BRCA1/2 and APC, are of primary importance in cancer risk assessment and treatment." (PMID 40113261, 2025). "Not surprisingly, ovarian (92.2%), pancreatic (86.7%), breast (84.4%), and prostate (83.3%) cancers exhibited the highest rates of biallelic BRCA1/2 alterations, indicating a strong link to biallelic gene loss." (PMID 40420266, 2025). "BRCA1 PV carriers were significantly younger at cancer onset and presented with more aggressive tumor subtypes, such as TNBC and higher Ki-67 values, than BRCA2 PV or WT carriers." (PMID 40422528, 2025). "Across cancer types, BRCA1/2 biallelic alterations were major contributors to HRD, especially in ovarian (45.9%/16.5%), breast (20.2%/11.9%), pancreatic (10.9%/12.7%), and prostate (5.9%/23.5%) cancers." (PMID 40420266, 2025). "While intratumoral heterogeneity has already been demonstrated in BRCA1-related tumors, its involvement in the pathogenesis of BRCA2-associated cancers requires additional studies." (PMID 40547808, 2025). "Almost 5%–10% of cases of BC are due to genetic mutations, and BRCA1 and BRCA2 are important genes associated with cancer progression." (PMID 40761498, 2025). "Among respondents with a history of cancer, all but one had a history of cancer and met the BRCA1/2 genetic testing criteria for HBOC diagnosis." (PMID 40900191, 2025). "Patients with BRCA1/2 PVs had a lower age of cancer onset (41.7 vs. 50.9 years; p < 0.0001) and lower menopausal status (18.9% vs. 51.1%; p < 0.0001) compared to WT patients." (PMID 40427118, 2025). "Investigating VUS, especially in ATM, is essential for understanding cancer predisposition mechanisms, developing targeted therapies and potentially recognizing ATM as BRCA3 due to its functional similarities with BRCA1/2." (PMID 40259910, 2025). "Genetic mutations are only counted in 5%–10% of cases of BC development, and BRCA1 and BRCA2 are important genes associated with cancer progression." (PMID 40755497, 2025).
cancer (continued). "Nine (9/89; 10.1%) of the BRCA1/BRCA2 MINAS cases within this review were reported by Leegte, van der Hout who reported a younger median age of cancer onset in BRCA1/BRCA2 MINAS at 40.8 years vs. 48 years for single BRCA1/BRCA2 carriers." (PMID 39843919, 2025). "In light of the critical importance of the BRCA1 gene in this specific subtype of cancer, we undertook an in-depth investigation of the BRCA1 regulon." (PMID 41354912, 2025). "For clinical application of ddPCR detecting BRCA1/2 CNVs in cancer tissues, a critical consideration is the establishment of appropriate cutoff thresholds to distinguish between normal and deletion classifications." (PMID 40725150, 2025). "BRCA1 catalyzes lysine 6-linked ubiquitination-mediated proteasomal degradation of GPX4, thereby sensitizing cancer cells to ferroptosis." (PMID 40342999, 2025). "In conclusion, our study demonstrates that OFD1 inhibition triggers the BRCAness phenotype, with significant implications for sensitizing BRCA1/2 proficient cancers to PARPi." (PMID 40764600, 2025). "These evidences highlight the need further investigations to elucidate the functional role of miR-525-5p and the rs8176318 SNP in the 3′-UTR region of BRCA1, as well as their influence on different genotypes and types of cancer." (PMID 39684686, 2024). "In individuals with family history of cancer, 5–10% carries PVs in BRCA2 gene and 1% in BRCA1 with a risk of developing PC of 5 and 10%, respectively." (PMID 38974244, 2024). "Similar results have been reported in multiple studies, implying that BRCA1 and BRCA2 were associated with the early onset of cancer." (PMID 38817903, 2024). "In cancer cells, increased expression of OLA1 inhibits apoptosis by interacting with breast cancer-associated gene 1 (BRCA1) and BRCA1-associated RING domain protein (BARD1)." (PMID 38889130, 2024). "In the context of pathogenic BRCA1/2 mutations or other HRD, cancer cells exhibit heightened sensitivity to PARP inhibitors due to synthetic lethality." (PMID 39376601, 2024). "On the other hand, human BRCA1 knockout (BRCA1-KO) fibroblast cells treated with exosomes isolated from the serum of cancer patients underwent cell transformation and formed tumours when transplanted into immunodeficient mice." (PMID 38252353, 2024). "Nonetheless, PARPi exhibit limited efficacy in the majority of HR-proficient BRCA1/2 wild-type cancers." (PMID 39156700, 2024). "Possible partial explanations are that these cancers have an age-of-onset past reproductive age and are less prevalent in males, or that BRCA1 is subject to some form of antagonistic pleiotropy." (PMID 37292653, 2024). "Cancer cells with DNA repair defects (e.g., BRCA1/2 mutant cells) are vulnerable to PARP inhibitors (PARPi) due to induction of synthetic lethality." (PMID 38767454, 2024). "SL interactions are exploited in cancer treatment e.g. BRCA1/BRCA2 and PARP, where targeting an SL partner of a cancer-specific mutation can selectively eliminate cancer cells." (PMID 39435285, 2024). "The most common cancer in relatives was BC (36.4% for BRCA1 and 44.5% for BRCA2 PV‐carriers), which was also the first cause of death from cancer in relatives (24.5% and 21%); however, this data was missing for around 20% of women." (PMID 39624976, 2024).
cancer (continued). "Previous studies showed that (+)-JQ136,37,38 and panobinostat can reduce BRCA1 protein expression and sensitize cancer cells to PARPi." (PMID 38993666, 2024). "The PARP inhibitors such as olaparib are also more efficacious in treating patients with homologous double-stranded DNA-repair, the primary impairment mechanism of cancers associated with BRCA mutations, further justifying our strategy for BRCA1/2 testing." (PMID 38439629, 2024). "While BRCA1/BRCA2 mutations modestly increase tumor mutation burden, their impact on the copy number landscape of cancer is notably more substantial." (PMID 39198848, 2024). "Cancer cells can survive a single alteration in BRCA1 or BRCA2 and subsequently adopt a backup DNA repair pathway." (PMID 38398147, 2024). "The inherited heterozygous deficiency of BRCA1 or BRCA2 increases the risk of breast, ovarian, and other cancers due to aberrant DNA repair." (PMID 38398147, 2024). "Because BRCA1 mutation occurs frequently in TNBC and diverse CAF phenotypes exist in cancer, we next performed scRNA-seq analysis to compare the characteristics of CAF between patients with TNBC BRCA1 mutation type (MT) and wild type (WT)." (PMID 38182557, 2024). "Inactivation of RAD52 in homologous-recombination-deficient BRCA1- or BRCA2-defective cells is synthetically lethal, and aberrant expression of RAD52 is associated with poor cancer prognosis." (PMID 38658755, 2024). "While occurrence of BRCA1 methylation was relatively rare across all cancer types, its clinical significance and potential therapeutic implications warrant further investigation." (PMID 39055334, 2024). "Our results also showed that BRCA1-mutant cancers exhibited higher cGAS-STING scores and higher pSTAT1 expression." (PMID 38167507, 2024). "Genetic counseling and testing were performed, utilizing a sequence analysis and deletion/duplication of a panel of 47 genes, including analysis of the BRCA1 and BRCA2 genes (Invitae Common Hereditary Cancers Panel, BRCA1/2 Panel, Invitae Corporation)." (PMID 38912178, 2024). "BRCA1 mutations common in RING, BRCT domains, and the middle region increase the risk of various cancers." (PMID 38543119, 2024). "Up to 40–80% of hereditary breast and ovarian cancers are due to BRCA1/BRCA2 germline mutations, and these genes are affected by germline or somatic genetic alterations in up to 8% of cancers." (PMID 39198848, 2024). "The DNA damage response (DDR) protein DNA Polymerase θ (Polθ) is synthetic lethal with homologous recombination (HR) factors and is therefore a promising drug target in BRCA1/2 mutant cancers." (PMID 38580648, 2024). "BRCA1/BRCA2/BRCA carrier cancer risks were specified by 47% (37/79) of websites (58%, 26/45 UKOs; 19%, 3/16 JCOs; 44%, 8/18 GTPs)." (PMID 39001386, 2024).
cancer (continued). "Concerning PARP inhibitors, current policy for most cancers allows reimbursement only when a BRCA1 or BRCA2 alteration has been confirmed." (PMID 38872153, 2024). "Research has shown that inhibiting CDK1, suppressed and transformed BRCA1 expression and phosphorylation transforms BRCA wild-type cancer cells into HR-deficient cells, making them more susceptible to synthetic lethality induced by PARPi." (PMID 39156700, 2024). "The primary outcomes were the presence of P/LP variants in the ATM, BRCA1, BRCA2, CHEK2, or PALB2 genes (cross-sectional analysis) or a diagnosis of cancer (cohort analysis)." (PMID 39320887, 2024). "Given that the CRISPR screens were performed separately for BRCA1−/− and BRCA2−/− backgrounds, we reanalyzed human cancer genomic data separating BRCA1 and BRCA2 tumors in OV and ER+ BC to identify candidate drivers for each gene individually." (PMID 39198848, 2024). "Two nonsense variants, specifically BRCA1 c.5470_5477del and BRCA2 c.5682 C > G, were identified in both healthy individuals and cancer patients." (PMID 38566028, 2024). "Of note, the BRCA1-defective cancer cell lines MDA-MB-436, HCC1937, and UWB1.289 showed increased sensitivity to POLAi ST1926 relative to BRCA1-proficient cell lines." (PMID 39191785, 2024). "Although BRCA1/2’s association with breast and OVC was confirmed two centuries ago, their involvement in other cancer types, such as prostate and pancreatic cancer, has recently come to the forefront." (PMID 38814507, 2024). "The defected BRCA1/2 is the specific marker for the use of synthetic lethal-based PARPi (poly ADP ribose polymerase inhibitors) therapy in cancer treatment." (PMID 38391958, 2024). "Our findings will support the rationale of implementing multi-gene panel testing beyond BRCA1/2 in Thai patients with HBOC-related cancers and provide more information on the Southeast Asian population." (PMID 38355628, 2024). "This is in line with a prior prospective clinical trial that revealed persistent cancer worries following preventive salpingectomy with delayed oophorectomy or standard salpingo‐oophorectomy in BRCA1/2 carriers." (PMID 38192174, 2024). "The contribution of BRCA1 and BRCA2 to cancer has been extensively studied, as families with these mutations show clustering of cancers in men." (PMID 39364320, 2024). "Patients with germline mutations of DNA damage repair genes (BRCA1, BRCA2, or NTHL1) had a later evolutionary onset of dissemination than patients with triple-proficient cancers (P = 0.03 by Wilcoxon’s test)." (PMID 38175731, 2024). "We identified a pathogenic frameshift variant (c.2475delC) in BRCA1 exon 11, likely responsible for the familial cancer history and a duplication of BRCA1 exon 20 (Ex20dup) in trans." (PMID 38195559, 2024). "In this context, it was recently proposed to rename the HBOC syndrome with a name perceived as more gender-neutral and inclusive of the broad cancer spectrum observed in BRCA1/2 PV carriers." (PMID 38339330, 2024). "A recent study used HRD-associated genomic patterns to provide evidence of HRD in 30 different cancer types, noting the presence of BRCA1 and RAD51C methylation." (PMID 39055334, 2024).
cancer (continued). "This suggests that the >40-year-olds were more frequently confronted with cancer risks arising from BRCA1/2 PVs combined with problems and worries of the previous BC diagnosis." (PMID 39446752, 2024). "Based on previous studies suggesting that the EXO1 nuclease is also implicated in reversed fork degradation in BRCA1-deficient cancer cells, we tested the effect of EXO1 knockdown in BRCA1-depleted U2OS cells." (PMID 38943334, 2024). "The overexpression of HMMR in the mouse mammary epithelium influences the tumor microenvironment and cancer cell phenotype, leading to an increase in the genesis of Brca1-mutant tumors." (PMID 38576486, 2024). "One mechanism that cancer cells use to develop PARPi resistance is by promoting the expression of the BRCA1 ∆11q isoform." (PMID 39062754, 2024). "Inherited mutations that impair HDR (e.g., BRCA1 and BRCA2 variants) are associated with elevated cancer risk, including early-onset breast cancer." (PMID 38824133, 2024). "For BRCA1 and BRCA2 carriers, the finding of a mutation has clear implications for cancer management, but for other genes, such as ATM, the management implications are less clear." (PMID 39543654, 2024). "Inhibition of PARP1 in cancer therapy is a recently adopted strategy to treat cancers where DNA repair is defective, such as HBOC caused predominantly by pathogenic variants in BRCA1 or BRCA2." (PMID 39062754, 2024). "PARP inhibitors (PARPi) have been shown to be effective in the treatment of cancers that present with HRR deficiency—for example, caused by inactivation of BRCA1/2." (PMID 38848470, 2024). "Genomic expression data published in The Cancer Genome Atlas (TGCA) show that POLQ is significantly overexpressed in cancer when BRCA1 or BRCA2 are altered." (PMID 38666816, 2024). "In BRCA1mut cancer tissues, the BRCA1 expression level was significantly higher than in BRCA2mut and BRCA1/2wt cancer tissues." (PMID 39080120, 2024). "BRCA1 and BRCA2 are two tumor-suppressor genes frequently mutated in breast, ovarian, prostate, pancreatic, and other cancers." (PMID 39007266, 2024). "Genetic factors play a role too, with inherited mutations like BRCA1 and BRCA2 increasing susceptibility to certain cancers." (PMID 39463536, 2024). "Based on the concept of synthetic lethality, PARPis exert their therapeutic effects on patients with BRCA1/2 mutant cancers." (PMID 38182579, 2024). "The observed correlations between BRCA1 promoter methylation and advanced cancer stage, as well as the Gleason score, suggest a potential involvement of BRCA1 methylation in the mechanism of tumor invasion." (PMID 39246954, 2024). "The research revealed that modifying the BRCA1 gene resulted in the suppression of cancer cell growth and heightened responsiveness of these cancer cells to chemotherapy." (PMID 38195537, 2024). "Breast cancer antigens 1/2 (BRCA1/2) are central enzymes in homologous recombination crucial for repairing double-strand breaks (DSB)." (PMID 38730642, 2024). "As of the current moment, PARP inhibitors have been investigated either as standalone treatments in cancers with depleted BRCA1/2 genes or in cancers exhibiting BRCA-like characteristics." (PMID 39318358, 2024). "BRCA1 and BRCA2 are tumor suppressors in several cancers and have been implicated in DNA repair in response to DNA breaks, transcription regulation, and cell growth control." (PMID 39338204, 2024). "Individuals with pathogenic variants of BRCA1 and BRCA2 are at higher risk of breast, ovarian, pancreatic and many other cancers." (PMID 39507757, 2024). "One patient (CA11) lacked a description of her clinical characteristics, since her treatment was conducted at another institution and her clinical history was unavailable; her cancer diagnosis and BRCA1 PV confirmation were corroborated." (PMID 38928478, 2024). "The utility of poly(ADP-ribose) polymerase (PARP) inhibitors in BRCA1/2-altered cancers similarly illustrates the importance of histologic context." (PMID 38938274, 2024).